SSX4 (SSX family member 4)
Description:
Could act as a modulator of transcription.
Synonyms: CT5.4
Tractability: No criterion of Open Targets' tractability assessment is met for any kind of drug.
Gene: Protein-coding gene on chromosome X (48,383,516 to 48,393,347, forward strand). Ensembl gene ENSG00000268009.
Subcellular location (Human Protein Atlas): Nucleoli; Nucleoplasm
Gene Ontology:
Molecular function: protein binding
Biological process: regulation of DNA-templated transcription
Cellular component: nucleus
Homologues: Orthologues: chimpanzee SSX3 (97% identical), macaque SSX7 (84% identical), mouse Ssxb9 (32% identical), mouse Ssxb8 (31% identical), mouse Ssxb1 (31% identical), mouse Ssxb15 (31% identical), mouse Ssxb6 (31% identical), rat Ssx1 (31% identical), mouse Ssxb10 (30% identical), mouse Ssxb5 (30% identical), mouse Ssxb14 (30% identical), mouse Ssxb3 (30% identical), and 5 more. Paralogues in human: SSX4B (100% identical), SSX7 (82% identical), SSX3 (81% identical), SSX1 (79% identical), SSX2 (79% identical), SSX2B (79% identical), SSX5 (78% identical).
Diseases named in the same sentence as SSX4 in open-access papers:
SSX4 is named in the same sentence as 32 diseases in open-access papers, as found by Europe PMC text mining. Sharing a sentence is not in itself a finding about the gene and the disease. The quoted sentences say what the papers report.
synovial sarcoma (33 papers, 2001 to 2025). "Fusion of SYT to SSX1, SSX2 and SSX4 causes inappropriate transcription of SSX sequences in synovial sarcoma that is characteristic of this tumour group." (PMID 12592363, 2003). "Fusion of the SYT gene on chromosome 18 with one of three homologous genes, SSX1, SSX2, and SSX4, on the X chromosome results in pathological tissue development of synovial sarcoma." (PMID 39583501, 2024). "Synovial sarcoma is associated with translocation causing a fusion between chromosomes SSX1, SSX2, and SSX4 and chromosome SS18, occurring in more than 90% of synovial sarcoma cases leading to the formation of SSX-SS18 oncogenes." (PMID 38188535, 2023). "For instance, beside the canonical fusion involving SS18 and SSX1 or SSX2, additional fusions involving SSX4 were called in 5/6 synovial sarcomas analyzed with the AMP-FPS panel." (PMID 32351889, 2020). "A specific t(X;18)(p11.2;q11.2) translocation resulting in fusion of genes between SYT, on chromosome 18, and SSX1, SSX2, or rarely SSX4 on chromosome X is detectable in 90% of synovial sarcomas." (PMID 29531545, 2017). "The observation that SSX4 is included within the synovial sarcoma gene set flagged in these analyses demonstrates proof of principle." (PMID 12592363, 2003). "The characteristic molecular hallmark of synovial sarcoma is the chromosomal translocation t(X;18)(p11;q11), which causes the fusion of the SS18 or Synaptotagmin (SYT) gene on chromosome 18 with one of the SSX genes (SSX1, SSX2, or SSX4) on the X chromosome." (PMID 40718269, 2025). "Nealy all synovial sarcomas (over 90%) have been identified with a chromosomal translocation between SYT and SSX genes, resulting in a fusion mutation of SYT to SSXs gene (including SSX1, SSX2, and SSX4)." (PMID 39748060, 2025). "In Synovial Sarcoma (SS), characterized by the fusion of the SS18 gene to either SSX1, SSX2, or SSX4, the expression of FOXM1 associates with poor prognosis and correlates with cell-cycle genes." (PMID 38946804, 2024). "The precise etiology of synovial sarcoma remains unclear, however, a characteristic SYT-SSX fusion gene, which results from a t(X;18) translocation and represents a fusion of SYT (at 18q11) with SSX1, SSX2 or SSX4 (at Xp11), can be detected in more than 90% of synovial sarcomas." (PMID 33562681, 2021). "Additionally, many other genes that have been previously related to synovial sarcomas, such as the SSX4 gene, EGFR and SALL2, components of the retinoic acid pathway (CRABP1 and RARG) as well as retinoic acid induced genes (IRX5 and TGFβ2), were also included in this module." (PMID 16503973, 2006). "Synovial sarcoma harbours a pathognomonic t (X; 18) translocation resulting in either SS18::SSX1, SS18::SSX2 or SS18::SSX4 fusion genes." (PMID 40666501, 2025). "Synovial sarcoma (SS) is a soft tissue sarcoma showing variable epithelial differentiation and is characterized by SS18::SSX1, SSX2, or SSX4 fusions." (PMID 36941503, 2023). "SSX genes were originally identified in synovial sarcomas with t(X;18) translocations, where SSX1 and SSX2 (and rarely SSX4) participate in oncogenic SYT-SSX fusions." (PMID 26380221, 2015). "The majority of cases of synovial sarcoma contain a t(X;18)(p11.2;q11.2) translocation that results in the fusion of the chromosome 18 gene SYT to three closely related genes SSX1, SSX2 and SSX4 on the X chromosome." (PMID 12592363, 2003). "Importantly, nearly all synovial sarcomas bear the translocation t(X;18)(p11.2;q11.2), representing the fusion of SSX (including SSX1, SSX2, or SSX4 isoforms) with SYT." (PMID 39748060, 2025). "In synovial sarcoma samples, there is a chromosome translocation that results in the replacement of C-terminal 8 amino acids of wild type SS18 by 78 amino acids of SSX genes (SSX1, SSX2 or SSX4) to form onco-protein SS18-SSX." (PMID 38678233, 2024).
synovial sarcoma (continued). "Synovial sarcoma is defined by a characteristic translocation t(X;18)(p11.2;q11.2), which is observed in > 95% of cases and results in the fusion of SS18 to the SSX1, SSX2, or SSX4 genes." (PMID 29415665, 2018). "The last segment is on chromosome X [coordinates 48,000,001–48,500,000], with three known genes belonging to the family of highly homologous synovial sarcoma X (SSX) breakpoint proteins showed expression values within the higher 2.5th percentile: SSX1, SSX4 and SSX4B." (PMID 27611585, 2016). "It is characterized by the typical translocation t(X;18)(p11;q11) that generates the fusion between the synovial sarcoma translocation, chromosome 18 (SS18 or SYT) gene on chromosome 18 and either synovial sarcoma, X breakpoint 1, 2 or 4 (SSX1, SSX2 or SSX4) genes on the X chromosome." (PMID 21609503, 2011). "Synovial sarcoma (SS) is a subtype of sarcomas characterized by a translocation between SSX18 and SSX1, SSX2, or SSX4." (PMID 40249565, 2025). "Synovial sarcoma (SS) is a rare soft tissue sarcoma that occurs in adolescents and young adults, with a pathognomonic t (X; 18) (p11.2; q11.2) chromosomal translocation, fusing the SS18 (formerly known as SYT) gene with the SSX1, SSX2, or SSX4 gene." (PMID 35126101, 2021).
melanoma (7 papers, 2010 to 2019). A malignant, usually aggressive tumor composed of atypical, neoplastic melanocytes. "We found that of these, those specific to GAGE and XAGE1 most significantly impeded melanoma cell migration and invasion and those specific to SSX4 and XAGE1 decreased the clonogenic survival of melanoma cells." (PMID 23625514, 2013). "Importantly, overexpression of miR-4731 inhibits SSX4 protein (pull-down target) resulting in a marked reduction in 2D colony formation in 3/3 melanoma cell lines." (PMID 27331623, 2016). "Interestingly SSX2 was detected in almost all melanoma tissues and derived cell lines (95%) compared to SSX4 (57%), SSX1 (38%), SSX5 (33%) and SSX3 (19%) expression." (PMID 24787708, 2014). "Our results suggest that GAGE, XAGE1 and SSX4 might each have a role in tumor progression and are possible therapeutic targets for the treatment of melanoma and other malignancies." (PMID 23625514, 2013). "Furthermore, members of the synovial sarcoma X breakpoint family (SSX) (melanoma growth promoters) were also down-regulated (e.g. SSX2, SSX4, and SSX4B) as a result of miR-4731 overexpression." (PMID 27331623, 2016). "27mer siRNA mediated silencing of SSX4 and XAGE1 using different duplexes that had similar specificity and efficiency of gene knock down, equally reduced clonogenic survival and migration of SK-MEL-37 melanoma cell-line, reducing the possibility of off-target effects." (PMID 23625514, 2013). "Again, as was found for the SSX2 class II peptides, CD4+ T cells could not recognize melanoma cells directly but were activated by APCs loaded with SSX4 antigen, which suggested that this peptide may not be presented through the endogenous pathway in tumor cells." (PMID 20981248, 2010).
breast carcinoma (6 papers, 2001 to 2022). "We also found frequent synchronous expression with MAGE, including LAGE-1 (46.2%) in oesophageal carcinoma, SSX-4 (46.7%) in gastric carcinoma, and SCP-1 (38.3%) in breast carcinoma." (PMID 11531257, 2001). "We found relatively high expression of SCP-1 (23.5%) and SSX-4 (20.6%) in gastric carcinoma, LAGE-1 (39.1%) and NY-ESO-1 (23.9%) in oesophageal carcinoma, and SCP-1 (34.1%) in breast carcinoma." (PMID 11531257, 2001). "We concluded that NY-ESO-1, LAGE-1, SCP-1 and SSX-4 genes may be promising candidates for cancer-specific immunotherapy in addition to MAGE, and that polyvalent cancer vaccines may be useful in cases of heterogeneous expressions of CTA genes in gastrointestinal and breast carcinomas." (PMID 11531257, 2001). "Of 16 CTAGs examined in the first panel of 42 breast cancer samples, seven antigens were found not to be expressed in any of the specimens: SSX2, SSX4, CTAG2, CAGE1, MAGEA1, MAGEA4 and MAGEA11." (PMID 17650306, 2007). "However, no humoral response was observed against SSX-4, MAGE-3, MAGEC1 and MAGEC2 in breast cancer." (PMID 23451156, 2013).
astrocytomas (3 papers, 2006 to 2013). "SSX expression has also been evaluated by RT-PCR in brain tumors in which SSX1 was only expressed in astrocytomas, while SSX2 was expressed in astrocytomas and oligoastrocytomas, and SSX4 was expressed in both of these as well as oligodendrogliomas." (PMID 20981248, 2010).
gastric cancer (3 papers, 2001 to 2020). A primary or metastatic malignant neoplasm involving the stomach. "Studies have shown that BCL2‐associated athanogene 1, melanoma‐associated antigen‐A1, MAGE‐A3, melanoma‐associated antigen‐C2, SSX family member 2, and SSX family member 4 genes are several representative genes that are specifically and highly expressed in stomach cancer." (PMID 32227453, 2020).
glioma (2 papers, 2006 to 2023). A benign or malignant brain and spinal cord tumor that arises from glial cells (astrocytes, oligodendrocytes, ependymal cells). "A strategy to limit BV-mediated transgene expression to tumor cells is the use of glioma-specific promoters such as SSX4 and FOS." (PMID 36992317, 2023).
multiple myeloma (2 papers, 2016). "SSX1, SSX2, and SSX4 are expressed in Hodgkin's lymphoma and head and neck cancer, while SSX1, SSX2, SSX4, and SSX5 are expressed in multiple myeloma." (PMID 27276714, 2016).
renal cell carcinoma (2 papers, 2018 to 2019). "It was recently reported that the SSX4 gene is also involved in such a translocation.Nonetheless, SS of the kidney can be first misdiagnosed as a renal cell carcinoma due to similar clinical presentation." (PMID 29751751, 2018).
ovarian tumor (1 paper, 2019). "In addition, aberrant expression of SSX-1, SSX-2, or SSX-4 was identified in 26% of ovarian tumor specimens, and SSX-1, SSX-2, and SSX-4 expression was detected in 2.5%, 10%, and 16% of 120 EOC specimens, respectively." (PMID 30609934, 2019).
tumor (12 papers, 2003 to 2025). "For instance, a SS case that was previously shown to be negative for SYT/SSX1 and SYT/SSX2 gene expression by conventional RT-PCR, was instead found to be SYT/SSX4 positive, as the sole fusion transcript expressed in this tumor sample, when the RT-PCR was redesigned." (PMID 29751751, 2018). "As each SS tumor harbors a unique breakpoint sequence within SYT and one of three SSX genes (SSX1, SSX2 and SSX4) forming the tumor-specific translocation t(x;18)(p11.2;q11.2), these breakpoint sequences can be used for ctDNA detection." (PMID 35565213, 2022). "At tumour sites, 33 (89%), 13 (35%), 16 (43%), 11 (30%), 10 (27%), and seven (19%) specimens expressed KK-LC-1, MAGE-A1, MAGE-A3, MAGE-A4, SSX4, and NY-ESO-1, respectively." (PMID 29666402, 2018). "At tumour sites, 18 (75%), eight (33%), 11 (46%), five (21%), three (13%), and four (17%) patients had KK-LC-1, MAGE-A1, MAGE-A3, MAGE-A4, SSX4, and NY-ESO-1 expression." (PMID 29666402, 2018). "Overall, our results suggest that inhibition on SSX4, XAGE1 and GAGE expression in cancer cell lines interferes with tumor cell migration and/or reduce cell viability." (PMID 23625514, 2013). "The examination indicated the hub genes in tumor samples, including GAGE2A, GAGE1, MAGEA9, CTAG1A, CTAG1B, and MAGEA1; and the hub genes in healthy ovarian tissue samples, including SPA17, MAGEC1, KDM5B, SSX4, and MAGEA9." (PMID 37835834, 2023).
cancer (6 papers, 2001 to 2023). A tumor composed of atypical neoplastic, often pleomorphic cells that invade other tissues. "According to these findings, in Intestinal GC, the chrXq28 band resulted in significantly associated activity between SSX1, SSX4 and SOLHLH1 MRs, which are involved in stem cell maintenance and are indicated as cancer and testis antigens." (PMID 36230884, 2022). "Another contributing factor could be the fact that a number of cancer-related genes, known as cancer/testis antigens (CTAs) that are located on the X-chromosome (MAGEA1, SSX1, SSX4, and CTAG1/2), are highly upregulated in PBL, which mainly affect male individuals." (PMID 26108914, 2015). "Effects of members of the MAGEA family on survival of cancer cell lines have been shown before, using a similar approach used in our study, but the effects of depletion of GAGE, XAGE1 and SSX4 have not been previously investigated." (PMID 23625514, 2013).
SSX4 also shares sentences with these, for which no sentence is quoted: lung carcinoma (3 papers); ovarian carcinoma (2); angiomatoid fibrous histiocytoma (1); brain tumour (1); colorectal cancer (1); esophageal squamous cell carcinoma (1); head and neck cancer (1); head and neck squamous cell carcinoma (1); Hodgkins lymphoma (1); infantile fibrosarcoma (1); intrahepatic cholangiocarcinoma (1); mesothelioma (1); myxoid liposarcoma (1); neuroblastoma (1); oligoastrocytoma (1); pancreatic cancer (1); small cell sarcoma (1); soft tissue rhabdoid tumor (1); soft tissue tumor (1); solitary fibrous tumor (1); stomach cancer (1).